STEAP4 (STEAP4 metalloreductase)
Diseases named in the same sentence as STEAP4 in open-access papers (continued):
Sharing a sentence is not in itself a finding about the gene and the disease.
tumor (continued). "Studies have shown that STEAP4 can promote PCa cell proliferation, and CXCR4 participates in the activation of various pro-cancer regulatory mechanisms, thereby promoting tumor proliferation and metastasis." (PMID 37221625, 2023). "Furthermore, STEAP4+, ADGRF5 + and CXCR4+, and SRGNC + fibroblast subgroups were closely related to tumor progression, tumor metabolism, and immunosuppression, indicating their contributions in PCa metastasis." (PMID 37221625, 2023). "Furthermore, the highly expressed DEGs of fibroblasts in LNM included immune-related genes (CCL21, CCL19, CCL2, and MYC), metabolism-related genes (STEAP4, FABP4, DPT, and APOE), and genes related to tumor proliferation and progression (RGS, CCN, and MYC)." (PMID 37221625, 2023). "Suppressing STEAP4 via knockdown techniques effectively attenuated the nuclear factor erythroid 2-related factor 2 (NRF2)–NAD(P)H:quinone oxidoreductase 1 (NQO1) signaling pathway, inducing apoptosis and autophagy, leading to substantial reductions in xenograft tumor growth." (PMID 40205952, 2025). "To validate the colocalization of STEAP4 and TFE3 in PCa patients, we applied in situ multi‐color immunofluorescence staining using antibodies against COL1A1, STEAP4, and TFE3, and observed STEAP4 and TFE3 double‐positive fibroblasts among the stromal cells within the tumor." (PMID 40917018, 2025). "This led us to speculate that the lack of significant differences in STEAP4 mRNA levels between normal and tumor tissues in OSCC could be attributed to genetic copy number alterations at the transcriptional level." (PMID 39668818, 2024). "Moreover, the expression levels of PTX3, TNFAIP6, and TNFAIP8L2 and the genetic alterations of TNFAIP1, TNFAIP6, and STEAP4 greatly impact the clinical outcome of HNC patients, likely by regulating the PI3K-Akt, Ras or other signalling pathways or by regulating tumour immune status." (PMID 34344926, 2021). "Therefore, blocking Steap4 in addition to supplementation with IL-22 could be a potential treatment regime to boost liver regeneration without triggering tumor progression after PVL." (PMID 38533053, 2024). "Moreover, a combination of IL-22 supplementation and Steap4 blockade could possibly serve as a novel therapeutic approach to boost liver regeneration without facilitating tumor progression after PVL." (PMID 38533053, 2024). "Thus, a combination of IL-22 supplementation and Steap4 blockade could potentially be applied as a novel therapeutic approach to boost liver regeneration without facilitating tumor progression after PVL." (PMID 38533053, 2024). "Genetic variability analysis revealed no alterations in STEAP4 in OSCC, whereas gene amplification was observed in HNSCC, suggesting tumor heterogeneity in STEAP4 among these cancer types." (PMID 39668818, 2024).
cancer (19 papers, 2004 to 2025). A tumor composed of atypical neoplastic, often pleomorphic cells that invade other tissues. "Single‐cell profiling identifies therapy‐resistant STEAP4+ myofibroblastic cancer‐associated fibroblast (SETAP4+ myoCAF)." (PMID 40917018, 2025). "STEAP4 (Transmembrane Epithelial Antigen of the Prostate 4) is a metalloreductase implicated in metabolism and cancer progression." (PMID 38791358, 2024). "Evidence in the literature associates STEAP4 with metabolic dysregulations in cancer and other diseases, where inflammation is a central hallmark." (PMID 33842315, 2021). "Through comprehensive single‐cell transcriptomic profiling of ENZ‐naïve and ENZ‐treated tumors, an expansion of ENZ‐resistant myofibroblastic cancer‐associated fibroblast (designated STEAP4+ myoCAF) is identified that correlates with adverse clinical outcomes." (PMID 40917018, 2025). "Inflammatory cytokines like IL17, have been linked with STEAP4 upregulation and cancer progression." (PMID 33842315, 2021). "For example, IL‐17 enhances the activation of the NF‐κB cancer‐promoting pathway by inducing STEap4‐dependent cytoplasmic copper uptake." (PMID 40391581, 2025). "In summary, STEAP4 exhibits differential expression in various tissues and can function as either a promoter or suppressor of cancer in different cancer types." (PMID 39668818, 2024). "Recently, there have been continuous discoveries regarding the function of STEAP4 in various types of cancer." (PMID 39668818, 2024). "These samples included 14 with low expression and 30 with high expression of STEAP4, with 4 pairs of corresponding adjacent tissues and cancers." (PMID 39668818, 2024). "The localization of STEAP4 in the mitochondria and differential expression in normal and cancer tissue make STEAP4 a potential candidate as a biomarker or a therapeutic target in CRC and androgen-dependent PCa." (PMID 33842315, 2021). "Next, we evaluated the impact of STEAP4 expression on the cancer metastasis and colonization in distant organ." (PMID 32060280, 2020). "A frequently used iron chelating drug, DFP, has been recently demonstrated to inhibit STEAP4 and as a result it could be used as a promising pharmacological regime against various types of cancer where STEAP4 overexpression is observed." (PMID 33842315, 2021). "The STEAP4 pathway was pharmacologically targeted in BC cells, with an iron chelating drug (Deferiprone) with simultaneous blockage of the HER2 pathway with the tyrosine kinase inhibitor Lapatinib, which demonstrated an additive therapeutic potential involvement of STEAP4 in cancer." (PMID 33842315, 2021). "STEAP4 promotes the uptake of copper, and copper is known to be enhanced in cancer tissues." (PMID 32060280, 2020). "Notably, STEAP4 has rarely been reported in other cancer types, such as BRCA, HNSCC, and OSCC." (PMID 39668818, 2024). "PPI network interaction analysis showed that STEAP4 closely interacts with the KLK family, implying that the KLK family may influence STEAP4's role in cancer." (PMID 39668818, 2024). "Among the top five KEGG pathways related to STEAP4, “valine, leucine, and isoleucine degradation” was negatively related, and “pathways in cancer,” “endocytosis,” “focal adhesion,” and “PI3K-Akt signaling pathway” were positively related." (PMID 36504560, 2022). "WARS, TMEM2, STEAP4, and ISL1 activated the “pathways in cancer” pathway in IHs." (PMID 36504560, 2022). "Remarkably, due to its membrane-bound localization and its high over-expression in neoplastic compared to non-neoplastic tissues, STEAP4 constitutes an ideal pharmacological target for cancer therapy." (PMID 33842315, 2021). "Interestingly, some novel BC related proteins (STEAP4, CLPTM1L, TMEM41A, DHCR24, etc.) were also discovered, which have been reported to be involved in other cancer types." (PMID 33842315, 2021).
metabolic disorders (6 papers, 2017 to 2025). "STEAP4 is a metal reductase that reduces Fe3+ to Fe2+ and Cu2+ to Cu+, promoting iron and copper transmembrane transport and maintaining their homeostasis, as well as playing a beneficial role against damage from inflammatory diseases and metabolic disorders." (PMID 36504560, 2022).
infection (4 papers, 2012 to 2025). The state of being infected such as from the introduction of a foreign agent such as serum, vaccine, antigenic substance or organism. "STEAP4, a gene encoding a plasma membrane metallo-reductase involved in the transport of iron and in the control of inflammatory cytokines was also highly induced by the infection." (PMID 22720048, 2012). "Activation of astrocytes is expected to occur in the presence of WNV, and this was observed in the BSCs following WNV infection because GFAP, VIM, LCN2, and STEAP4 all showed enhanced expression following infection with WNV compared with the mock-infected samples." (PMID 35412380, 2022). "Conversely, infection-induced upregulation of CXCL10, STEAP4, C3 and GFAP was significantly reduced in CK2βVas-/- mice." (PMID 40929057, 2025). "In Huh7 cells, increased expression of acute-phase proteins, such as C-reactive protein and serum amyloid A1, was observed with the progression of infection, whereas FFAR2 and STEAP4 with metalloreductase activity showed significantly higher upregulation than other genes." (PMID 34899651, 2021).
cardiovascular disease (3 papers, 2020 to 2025). "Potentially, STEAP4 could be involved in the previously identified association between insufficient sleep and increased risk of cardiovascular disease." (PMID 41239200, 2025).
bacterial infection (1 paper, 2008).
retinopathy (1 paper, 2025). "STEAP4 expression was gradiently increased from low levels in diabetics without retinopathy to successively higher levels in diabetics with more severe disease." (PMID 40002391, 2025).
STEAP4 also shares sentences with these, for which no sentence is quoted: Arthritis (3 papers); Hepatic steatosis (3); metabolic syndrome (3); type 2 diabetes (3); chronic kidney disease (2); iron overload (2); prostate tumor (2); pulmonary arterial hypertension (2); pulmonary hypertension (2); allergic rhinitis (1); Alzheimer disease (1); breast tumor (1); cardiac disease (1); chronic lymphocytic leukemia (1); Cirrhosis (1); colon mucinous adenocarcinoma (1); COVID-19 (1); endometriosis (1); glioma (1); Hepatitis (1); hyperferritinemia (1); Hypertension (1); idiopathic pulmonary arterial hypertension (1); inflammatory bowel disease (1); ischemia (1); ischemic cardiomyopathy (1); leiomyoma (1); lymph node metastasis (1); myocardial infarct (1); neurodegenerative disease (1).
A further 10 diseases each share a sentence with STEAP4 in 1 paper.